BRAF (B-Raf proto-oncogene, serine/threonine kinase)
Diseases named in the same sentence as BRAF in open-access papers (continued):
Sharing a sentence is not in itself a finding about the gene and the disease.
melanoma (continued). "Moreover, Snail1 expression was higher in BRAFV600E-mutant melanomas compared with BRAF wild-type melanoma cells and biopsies, and its expression decreases upon an autophagy blockade by TTCC blockers." (PMID 32046241, 2020). "In addition, studies have shown that BRAF and NRAS mutant melanomas have similar metastasis rates and they are slightly more likely to metastasize than BRAF and NRAS wild-type melanomas." (PMID 32894090, 2020). "On the contrary, for nodular melanomas (NM), lentigo malignant melanoma (LMM), ALM, uveal melanoma (UM), MM, primary melanoma, and undifferentiated melanoma there was no relation found to BRAF gene mutations and histological subtypes." (PMID 31274706, 2020). "Thus, PC activation should be further investigated as a potential metabolic target to overcome acquired resistance onset in BRAF-mutant melanoma." (PMID 31819183, 2020). "Several studies showed upregulation of OXPHOS in BRAF inhibitor-resistant melanoma cells, suggesting that targeting mitochondrial respiration could be an effective strategy to overcome MAPK inhibitor resistance." (PMID 33007949, 2020). "In contrast, CDKN2A promoter hypermethylation occurs most frequently in NRAS-mutant melanoma (87.7%) and is less common in melanoma with BRAF mutations (67.0% with CDKN2A promoter methylation) and in melanomas with NF1 mutations (77.3% showing CDKN2A promoter methylation)." (PMID 33076392, 2020). "Having demonstrated the downregulation of surface PD‐L1 expression by BRAF inhibition, we hypothesized that vemurafenib should trigger increased activation of T cells interacting with vemurafenib‐pretreated melanoma cells." (PMID 32330348, 2020). "These experimental evidences suggest that uPAR levels could predict outcome of targeted therapy in patients affected by BRAF mutant melanoma." (PMID 32528879, 2020). "This study confirmed the co-occurrence of BRAF mutation with IDH1 mutation previously observed, and demonstrated that mutant IDH1 conferred in a BRAF V600E melanoma cell line acquired in vivo growth activities and enhanced activation of the MAPK and STAT3 pathways." (PMID 32850962, 2020). "Surprisingly, to the best of our knowledge, no secondary mutations in BRAF have been found in melanomas, though there is an example of a BRAF secondary mutation in a V600E brain tumor, namely L514V, and in this case it conferred resistance to dabrafenib." (PMID 32605090, 2020). "The inhibitory effect of SB202190 on ERK activity was observed in human melanoma cell lines carrying BRAF V600E mutation (A375, G361, Colo-800), but not in melanoma cells with NRAS mutations (MEL-JUSO, SK-MEL-30, IPC-298)." (PMID 32531927, 2020). "To test whether Nedd4-mediated VDAC2/3 degradation is also essential for the suppression of erastin-induced ferroptosis in melanoma cells carrying wt BRAF, we knocked down Nedd4 or overexpressed VDAC2/3 in MeWo cells." (PMID 31974380, 2020). "It was shown that BRAF mutant melanoma cells may display increased oxidative metabolism and increased dependency on mitochondria for survival." (PMID 33255659, 2020). "BRAF inhibitors are typically used in combination with inhibitors of MEK, the downstream target of BRAF, in order to delay the development of resistance to BRAF inhibitor monotherapy as in the current standard of care for late-stage BRAFV600E melanoma, dabrafenib and trametinib." (PMID 32092958, 2020). "The primary tumour characteristics of our study show that 89% (24/27) of the response evaluated melanoma metastases were BRAF-WT (wild-type or non-mutated)." (PMID 31936897, 2020). "Nanolipolee-007 also reduced melanoma metastasis formation in spontaneous metastasis animal models, irrespective of the BRAF mutational status of the circulating tumor cells." (PMID 33121001, 2020).
melanoma (continued). "In addition, the relevance of the BRAF status of melanoma cells in response to EOs is worthy of further investigation to shed light on this issue." (PMID 32948083, 2020). "In addition, increased levels of folic acid, which can occur through increased flux of carbons from serine synthesis through the folate cycle, is a possible mechanism of resistance to MEK inhibitors in BRAF inhibitor-resistant melanomas." (PMID 33511334, 2020). "Therefore, the role of BRAF and also NRAS mutations alone or in combination in the metabolic switch of melanoma needs to be further investigated." (PMID 33091721, 2020). "Melanoma patients carrying an oncogenic NRAS mutation represent 20% of all cases and present worse survival, relapse rate and therapy response than patients with wild type NRAS or with BRAF mutations." (PMID 31906480, 2020). "Additionally, in melanoma cells various transcription factors regulate in parallel BRAF and glycolysis pathway." (PMID 32509589, 2020). "Therefore, we aimed to identify the alternative autocrine ligands potentially triggering NRP1-dependent resistance to BRAF-targeted therapy in melanoma." (PMID 32784465, 2020). "In addition, birinapant, an SM, in combination with TNFα, was reported to inhibit the growth of melanoma, including the serine/threonine-protein kinase B-raf (BRAF) inhibitor-resistant cell line." (PMID 32325691, 2020). "Summary of selected targeted therapy trials in BRAF-mutant advanced melanoma." (PMID 32760738, 2020). "The effectiveness of immune checkpoint inhibitors (cytotoxic T-lymphocyte-associated antigen 4 (CTLA-4) and programmed death 1 (PD-1)) and targeted therapies (BRAF–MEK inhibitors) in melanoma patients with brain metastases have made a significant change in melanoma treatment." (PMID 33282420, 2020). "In addition, patients with BRAF-mutant melanoma that exhibited high level of autophagy were characterized with poorer response to BRAFi." (PMID 32340261, 2020). "In addition, vemurafenib (BRAF inhibitor) resistant melanoma lines (M229, M238, Pt48) demonstrated higher sensitivity towards BEZ235 + selumetinib therapy previously." (PMID 33081092, 2020). "For this reason, the aim of revising all studies evaluating the frequency of mutations of BRAF, NRAS, and KIT genes are to determine the correlation of the clinical-pathological characteristics of melanomas, and the demographic characteristics of the analysed populations." (PMID 31274706, 2020). "Indeed, nevi remain growth-arrested for decades and rarely progress into melanomas presumably because aberrant BRAF signaling induces a robust senescence response mediated by upregulation of the cell cycle inhibitor p16." (PMID 33212834, 2020). "This custom ddPCR panel would have a predicted coverage of ~80% of cutaneous melanomas based on the skin cutaneous melanoma TCGA dataset which gives a BRAF/NRAS coverage of ~70% and the fact that TERT promoter mutations are found in around ~29% of BRAF wild-type melanoma patients." (PMID 32785074, 2020). "Indeed, Prahallad and co-workers revealed that SHP-2 knockout clones of SK-Mel888 BRAF(V600E) mutant melanoma cells were unable to confer Vemurafenib resistance, following HGF, fibroblast growth factor 9 (FGF9), and stem cell factor (SCF) exposure." (PMID 33003469, 2020). "Furthermore, vemurafenib treatment increases the production of transforming growth factor β (TGF-β) by melanoma cells; TGF-β, in turn, causes CAFs’ activation and increased fibronectin production, involved in BRAF inhibitors’ resistance." (PMID 33036192, 2020). "In BRAF-mutant melanomas, the use of drugs targeting mitochondrial biogenesis and mitochondrial metabolism in combination with BRAFi/MEKi may enhance and delay BRAFi/MEKi-induced cell death and resistance in melanoma, respectively." (PMID 32528879, 2020).
melanoma (continued). "The first BRAF inhibitor, sorafenib (Nexavar®, developed by Bayer Pharma AG, Berlin, Germany, and Onyx Pharmaceuticals, San Francisco, CA, USA) was developed for the treatment of melanoma." (PMID 32213878, 2020). "In a melanoma cell line model, it has been shown that mutant BRAF inhibition may increase DNA damage by downregulation of NHEJ pathway genes, including XRCC6, XRCC5, and PRKDC." (PMID 33195430, 2020). "YAP promotes PD-1 expression driving immune evasion in BRAF inhibitors-resistant melanoma." (PMID 33212834, 2020). "Interestingly, a recent study showed that melanoma cell lines resistant to a BRAF inhibitor (PLX4032) display increased CDC42 activity compared to non-resistant melanoma cells." (PMID 33072757, 2020). "Importantly, dietary glutamine supplementation increases survival in a transgenic melanoma model and improves therapeutic response to BRAF inhibition." (PMID 32620791, 2020). "Anti-PD-1 treatments are considered an effective option in advanced melanoma patients, regardless of BRAF mutation." (PMID 32731406, 2020). "A similar strategy has been pursued also in BRAF-wt melanoma." (PMID 33574893, 2020). "In addition, several studies support the notion that MAPK inhibitor treatment in BRAF mutant melanoma actually promotes the reprogramming of melanoma cells towards a CAF/myofibroblast-like phenotype that is a source of drug resistance and tumor progression." (PMID 32466585, 2020). "Therefore, it is of importance that also in melanoma the miR-622-target KRAS was shown by our group to strongly affect BRAF-inhibitor resistance." (PMID 31906510, 2020). "Patients with BRAF-WT melanomas largely lack molecularly targeted treatment options." (PMID 32764384, 2020). "To assess whether the prognostic classifier was an independent indicator in distinct subgroups, we checked the effect of BRAF and NRAS mutation or wild-type on the prognostic ability for melanoma in TCGA cohort." (PMID 33005180, 2020). "In addition, BRAF inhibitors are also used to treat colorectal cancer, whereas its efficacy is significantly lower than that of melanoma." (PMID 32476297, 2020). "BRAF and MEKis have revolutionized the management of BRAFV600‐mutated melanoma patients." (PMID 32056395, 2020). "Of note, the activation of MET by HGF has been suggested as a potential mechanism of acquired tyrosine kinase inhibitor (TKI) resistance to gefitinib in epidermal growth factor receptor (EGFR)-mutant non-small cell lung cancer (NSCLC) and to vemurafenib itself in BRAF-mutant melanoma." (PMID 33553157, 2020). "Selumetinib was found to have an inhibitory effect on S6 activation after 24h treatment in an earlier study on BRAF mutant melanoma cell lines, which may contribute to the enhanced effect of the combination when compared to single treatment." (PMID 33081092, 2020). "Despite recent advances in the systemic treatment of extracranial metastases by using BRAF-targeted therapy in patients harboring BRAFV600E-mutant melanomas or inhibitors targeting immune checkpoint molecules, the treatment of melanoma brain metastases remains a major challenge." (PMID 32117271, 2020). "The mutated BRAF gene encodes for an active BRAF protein inducing the constitutive MAPK pathway activation and subsequently promoting cell proliferation and preventing apoptosis in melanoma cells." (PMID 32013263, 2020). "Importantly, A375 melanoma cells that acquired resistance to BRAF inhibitors were comparably sensitive to SBI-756 as the parental cell line in vitro." (PMID 32517051, 2020). "The combination of a BRAF inhibitor with either an anti-PD1 or anti-PDL1 checkpoint inhibitor has been shown to increase T-cell infiltration, the ratio of CD8+ T cells to regulatory T cells, and T-cell activity, compared with either agent alone in a murine model of BRAF-mutant melanoma." (PMID 32645969, 2020).
melanoma (continued). "Considering that around half of melanomas harbour mutations in BRAF V600E, the first targeted therapies approved by the U.S. Food and Drug Administration (FDA) were vemurafenib and dabrafenib, followed by BRAF/MEK inhibitor pairing treatment." (PMID 33203119, 2020). "However, to our knowledge no previous study investigated the capability of RTIs to mitigate drug resistance to target therapy in BRAF-mutant melanomas." (PMID 32933538, 2020). "Thus, Gal-1 autocrine signaling via NRP1 represents a druggable mechanism mediating melanoma cell resistance to BRAF inhibitors." (PMID 32784465, 2020). "In agreement, we observed marked elevation of glycolysis in addition to high OXPHOS, as shown by higher basal OCR, ATP-R, and activity levels of OXPHOS complexes, in three out of four of our melanoma cell lines (a BRAF/NRAF/NF1-wild-type and two BRAF-mutated melanoma cell lines) compared to HDFs." (PMID 33007949, 2020). "For melanoma patients without BRAF mutations, targeted treatments have shown no significant benefit." (PMID 31839677, 2020). "We wanted to screen for small molecules that could be used to enhance immune recognition in a BRAF mutant melanoma cell model." (PMID 32231230, 2020). "Two studies have assessed BRAF protein expression in melanoma." (PMID 32393282, 2020). "While the contribution of somatic BRAF/NRAS mutations to melanoma is very important, our study did not reveal any evidence of germinal BRAF/NRAS mutations." (PMID 33748184, 2020). "Additionally, two large omics studies have highlighted the role of glutamate-mediated activation of G-protein coupled receptors (GPCRs) in conferring BRAF inhibitor resistance in melanoma cells." (PMID 32937954, 2020). "Very few studies have investigated the role of BRAF expression in melanoma." (PMID 32393282, 2020). "The dual targeting of BRAF and mTOR signaling pathways, which are essential for the growth of a significant proportion of melanomas, suggested that pyridinyl imidazole compounds could have a therapeutic potential in BRAF-mutated melanoma." (PMID 32531927, 2020). "Pre-clinical and clinical studies show that targeting BRAF using RAF-selective inhibitors results in remarkable tumour shrinkage in BRAFV600E mutant melanomas; however, many of the treated patients exhibit therapy resistance due to the highly heterogeneous tumour profile." (PMID 32613561, 2020). "Em meta-análise recente que inclui 5 estudos clínicos randomizados e 2.317 pacientes com melanoma em uso dos inibidores BRAF e MEK, demonstrou-se que o tratamento concomitante com esses inibidores está associado a risco aumentado de embolia pulmonar (4,4x), queda na FEVE (3,72x) e HAS (1,5x)." (PMID 33295473, 2020). "For most of the cases where the patient has metastatic or non-resectable melanoma, various assays to determine the status of the mutated BRAF need to be performed to ascertain disease progression and subsequently, an appropriate treatment." (PMID 32213878, 2020). "In the light of these evidences TERT aberrant expression may impact on the establishment of resistance to target therapy in BRAF-mutant melanomas." (PMID 32933538, 2020). "NF1 mutations are present in <15% of melanoma cases and may be present together with NRAS/BRAF mutations." (PMID 32054078, 2020). "The net effect of these genetic alterations is a shift in the phenotype of BRAF inhibitor-resistant melanoma cells, resulting in an epithelial-to-mesenchymal transition (EMT), characterized by changes in cell–cell adhesion, cell-matrix adhesion, cellular polarity, and the cytoskeleton." (PMID 33003483, 2020). "In melanoma, the transfer of PDGFR-β mediated by EVs released by melanoma (donor) cells caused an activation of the PI3K/Akt pathway and escape from the MAPK pathway on BRAF mutated (recipient) cells, contributing to cellular proliferation and inhibition of apoptosis." (PMID 32384712, 2020).
melanoma (continued). "For the first time, Sumimoto H. and co-workers, using the U0126 MEK inhibitor and lentiviral BRAF(V600E) RNA interference, found that the oncogenic BRAF favors melanoma immune escape increasing production of IL-6 and IL-10 which increase T-cell stimulatory function of dendritic cells." (PMID 32604720, 2020). "Moreover, the coexistence of mutated BRAF and gain-of-function MAP2K1/MAP2K2 mutations was detected in two melanomas and resulted in higher resistance to MEK inhibitors." (PMID 32847629, 2020). "A recent study revealed that bleomycin-based ECT is more effective on BRAF mutated malignant melanoma cells in comparison with WT (non-mutated) melanoma cells." (PMID 31936897, 2020). "Furthermore, BRAF and NRAS mutations are mutually exclusive, as well as TERT C250T and C228T, and then, a maximum of two mutations will be tested in plasma for each melanoma patients, making feasible the dPCR approach proposed in this study." (PMID 33122747, 2020). "However, NF-κB pathway is not the only pathway that is influenced by AEBP1 overexpression in melanoma patients with resistance to BRAF inhibition." (PMID 32565808, 2020). "The effects of knocking down AURKB and HI-511 treatment on wild-type BRAF melanoma cell line (SK-MEL-31) were detected by crystal violet staining assay, the results revealed that knocking down AURKB and HI-511 treatment could suppress SK-MEL- 31 growth." (PMID 32863956, 2020). "Combining drugs that target proapoptotic BCL-2 family proteins with BRAF inhibitors in BRAFV600E-mutated cancers sensitizes melanoma cells to apoptosis but has not been shown to reverse resistance that is acquired over time." (PMID 32411231, 2020). "Similarly, c-Jun was shown to mediate PD-L1 upregulation in BRAF inhibitor-resistant melanoma cells." (PMID 32024543, 2020). "In addition, our in vitro data with viability assays and primary sphere assays show a trend of BRAF-WT melanomas being more sensitive that is, sensitive at a lower dose to this combination." (PMID 32764384, 2020). "Targeting mutant BRAF can lead to a strong response in melanoma patients." (PMID 32531927, 2020). "Untreated melanoma is not particularly immunogenic, but treatment with BRAF inhibitors causes a transient increase in antitumor immunogenicity, with recruitment of T-cells and natural killer (NK) cells and a reduction in regulatory T-cells (Tregs)." (PMID 33003483, 2020). "Therefore, BRAF inhibition promotes a remodeling of melanoma microenvironment, by which the tumor cells escape to pharmacological blockade." (PMID 33036192, 2020). "This sequence of treatment is commonly used for BRAF mutant melanoma in Australia." (PMID 33339135, 2020). "Expression of mutated BRAF (v-raf murine sarcoma viral oncogene homolog B1) V600E mutation induces the transcription of IL1A and IL1B in papillary thyroid carcinoma cells, melanocytes, and melanoma cell lines and this induction can be inhibited by vemurafenib." (PMID 32635472, 2020). "BRAF mutation per se is not sufficient to promote melanoma formation, but several studies have highlighted a crucial role of the mutant protein in disease progression." (PMID 33036192, 2020). "Since 2011, however, the rules of the treatment of stage IV melanoma have been completely rewritten, with the introduction of targeted therapies with BRAF and MEK inhibitors, and immunotherapy with the anti CTLA-4 ipilimumab and the anti-PD-1 nivolumab and pembrolizumab." (PMID 32850962, 2020). "Somatic mutations in BRAF, most commonly V600E or V600K, are the most frequent oncogene mutations in melanoma, and also appear recurrently in colorectal cancer, non-small cell lung carcinoma, and many other cancers." (PMID 32413516, 2020).